TNF (tumor necrosis factor)
Diseases named in the same sentence as TNF in open-access papers (continued):
Sharing a sentence is not in itself a finding about the gene and the disease.
infection (continued). "WT mice which received Stat1−/− bone marrow responded to infection with a systemic cytokine storm, i.e elevated serum levels of almost all measured cytokines and chemokines (IL6, IL22, TNFα, MCP1, IL10, Rantes, IP10 and MCP3)." (PMID 22719255, 2012). "Mif−/− mice presented higher parasite burden in brains and peritoneal macrophages and reduced plasma concentrations of IL-12, TNF, IFN-γ, IL-1β, and nitrite during infection." (PMID 22496958, 2012). "Levels of pro-inflammatory cytokines (TNF-α, IFN-γ and GM-CSF) are elevated as early as 1 h while most other cytokines peak within 2 h of infection." (PMID 23009705, 2012). "Infection of primary and C2C12 permanent SkMCs with these parasites in the absence of l-NIL confirmed that IFN-γ alone or in combination with TNF inhibited parasite propagation at 2 and 4 days post infection." (PMID 23024821, 2012). "For standard dosing regimen of anti-TNF agents, a meta-analysis studying the association of short-term use of anti-TNF agents with infections and malignancies showed that there was a small risk of overall infection and no increased risk of serious infection or malignancy." (PMID 22509259, 2012). "Starting at day 1 post infection, control animals also had higher levels of several cytokines, including IL-1α, IL-1β, IL-6, IL-12p70, and IFN-γ in plasma, additionally IL-17 and TNF-α and chemokines (KC, MCP-1, MIP-1α) were elevated in lungs." (PMID 22448290, 2012). "Consistent with previous studies and associated with the classical activation M1 phenotype, transcription of TNFα (up to 5), CXCL10 (IP10), CCL2 (MIP1α), and other chemotactic cytokines such as CCL3 (up to 6.8) and CCL4 was upregulated following infection." (PMID 22928052, 2012). "Compared with IFN-γ stimulation alone, TNF-α (10 ng/ml) and IFN-γ (10 ng/ml) combination induced significantly higher iNOS mRNA expression at 36 h after Cm infection, in parallel with increased inhibition of Cm growth." (PMID 22745717, 2012). "Both mouse strains displayed similar levels of TNF and IFN-γ in sera at 9 and 15 days post-infection." (PMID 22348160, 2012). "At one week of infection, viral clearance of both MCMV and MCMVdie1 has mostly taken place in all organs tested with the levels of TNFα having returned to mock levels except for a residual higher level in the spleen for the MCMV infection." (PMID 22952450, 2012). "Taken together, these results indicate that through its key role in regulating TNF and IFN-γ, NFATp controls a major checkpoint in T cell cytokine expression required for control of MTb infection in the mouse." (PMID 22844476, 2012). "Compared with uninfected placental villous explants, AD169 infection of explants at an MOI of 0.2 pfu/ml resulted in significantly elevated expression of MCP-1 and TNF-α (p = 0.0003 and p<0.0001 respectively)." (PMID 23300810, 2012). "In fact, an approximate one-week delay in the transcription ratio for CD3, TNF-α, IFN-γ, iNOS, IL-10 and arginase I was observed in IL-12p40KO mice at the third and fourth weeks after infection." (PMID 23152844, 2012). "FasL and TNF-α were induced most robustly, but TRAIL was only mildly induced in response to infection." (PMID 22279582, 2012). "During infection with T. gondii (and infections with other intracellular pathogens) the production of IL-12, IFN-γ and TNF by DCs is essential to control pathogen growth." (PMID 22693634, 2012). "More particularly, IL-12, IFN-γ, TNF-α and IL-6 levels were quantified by ELISA in P2Y2+/+ and P2Y2−/− BALFs at days 8, 10 and 12 post-infection." (PMID 23185614, 2012). "We investigated the release of TNF (n = 8 donors) and IL-12p40 (n = 6 donors) from monocyte-derived macrophages (MDM) during 48 hours of infection with M. tuberculosis strains of various lineages at 48 hours." (PMID 22916219, 2012). "Secretion of tumor necrosis factor alpha (TNF-α) and interleukin 10 (IL-10) was significantly induced during the infection of HLA-B27-transfected U937 cells with the mutants." (PMID 22470519, 2012).
infection (continued). "TNF-α and IL-10 expression were also significantly elevated in PBMCs isolated from calves on day 4 post-BHV-1 infection but these responses were similar when comparing WMS and PA calves." (PMID 22435642, 2012). "The cytokines previously shown to be important in protection against B. pseudomallei, such as TNF-α, IFN-γ and IL-12p70, were detected at moderate levels in CpG treated BALB/c mice throughout the course of infection." (PMID 22448290, 2012). "Resistance to infection by L. major is mediated by IFN-γ, TNF-α, and activation of macrophages to produce nitric oxide." (PMID 22203861, 2012). "After infection with each virus (104 PFU), lungs from three mice per group were collected at day 1, 3, 5 and 7 p.i. and the levels of cytokines (IL-6, IL-1β, TNF-α, IFN-γ) and chemokines (MIP-2, MIP-1α, MCP-1) in lungs were analyzed by ELISA." (PMID 22719870, 2012). "At 24 hours after infection, PAR-1 KO mice had substantially lower plasma levels of TNF-α and MCP-1 (P <0.001) and a trend toward lower IL-6 concentrations (P = 0.08) when compared with WT mice." (PMID 23270594, 2012). "MCMV replication promotes production of pro-inflammatory cytokines and chemokines (IL-12p70, IFN-γ, TNF-α, MIP-1α, IL-6, and MCP-1), which peak between 24 and 40 hours post-infection in the blood depending on the cellular source of the cytokine." (PMID 22649570, 2012). "As the course of disease progresses, IL-6, TNF-α, MCP-1, and MIP-1α are nearly undetectable in the lungs and spleens by day 7 after infection." (PMID 22428026, 2012). "We therefore sought to establish an equivalent level of infection (PFU per gram of tissue) by adjusting the initial infectious dose of the inoculums and determining TNFα production." (PMID 22952450, 2012). "Serum TNF-α levels were elevated in response to MCMV infection at both 40 h and 48 h post-infection in WT mice (69±10 and 63±17 pg/mL, respectively)." (PMID 22723955, 2012). "The mRNA expression of TNF-α, IFN-β, RANTES, IP-10 and the housekeeping gene, β-actin was quantified using quantitative RT-PCR at 3, 6 and 24 hours post-infection." (PMID 23226456, 2012). "In our infection model, PD-1high CD8 T cells produced less pro-inflammatory cytokines IL-2, IFN-γ and TNF-α in response to ex-vivo stimulation with immunodominant SSIEFARL peptide as compared to the PD-1medium CD8 T cell pool." (PMID 22808056, 2012). "While AD169 infection of placental explants produced a significant MCP-1 and TNF-α response compared with mock-infected explants, these results were not reflected with the wild-type Merlin strain." (PMID 23300810, 2012). "Infection of UNC93B1 mutant mice revealed reduced production of systemic and liver proinflammatory cytokines including IFN-α, IFN-γ, IL-12 and TNF-α when compared to wild-type." (PMID 22723955, 2012). "Similar to what has been reported during macrophage infection with virulent M. tuberculosis, it is possible that mycobacterial RNA induces TNF-R2 shedding thus rendering monocytes unresponsive to TNF-α." (PMID 22253841, 2012). "Our data also showed a correlation between the amounts of triple positive IL-2+TNFα+IFNγ+ vaccine-specific CD4 T cells induced by immunization and the subsequent level of protection against infection with M.tb." (PMID 22768165, 2012). "Specifically, secretion of IL-6 and TNF-α from MDM and IL-6 and IL-8 from ATII cells increased at 20 h post-infection." (PMID 23293773, 2012). "Infection of pDCs with myxoma virus also induced the production of comparable levels of IFN-α and TNF." (PMID 22606294, 2012). "Administration of MSCs led to a 50% reduction in the expression of TNFα (p = 0.01), a 34% reduction of IL1β (p = 0.02) and a 60%reduction of IL6 (p = 0.006) 7 days after infection." (PMID 22815907, 2012). "In our study, MCP-1, TNF-α and CSF3 of WD infected PAM were all downregulated, when compared with KO infection, which is likely to increase S. zooepidemicus pathogenesis." (PMID 22567158, 2012).
infection (continued). "AM from FP-treated mice showed impaired expression of infection induced TNF-alpha, IP-10 (CXCL-10), and interleukin 6 (IL-6), and AM also showed a trend towards impaired intracellular pathogen control following in vivo infection." (PMID 22651370, 2012). "In this study the plasma levels of three proinflammatory (TNF-α, IFN-γ, IL-4) and one anti-inflammatory cytokine (IL-10) during a primary infection with Mycoplasma mycoides subsp." (PMID 22533922, 2012). "Compared to full-term lambs, lungs of preterm lambs had a heightened pro-inflammatory response after infection, with significantly increased MCP-1, MIP-1α, IFN-γ, TNF-α and PD-L1 mRNA." (PMID 21827668, 2011). "Based on our previous report, C. pneumoniae-induced secretion of the cytokines TNF and IFNγ and the chemokines KC and MCP-1 depended on MyD88 three days post infection." (PMID 22096480, 2011). "Monitoring chemoattractive factors, especially those under the regulation of TGF-β (i.e. IL-1β and TNF-α), would help delineate the pro- or anti-inflammatory role of TGF-β in intramammary infection with different strains of S. aureus." (PMID 21884610, 2011). "After 48 h of infection, cells were transfected with CYLD expression plasmid or left untransfected and treated with TNFα for 10 min after 30 h of transfection." (PMID 21408173, 2011). "Therefore, we investigated whether various activation signals, such as proinflammatory stimuli (TNF-α or IL-2 or IL-15), or signals that mimic infection (LPS, SEB or PMA), influence the cell surface expression and active secretion of HMGB1 by human cord blood cells." (PMID 21915243, 2011). "Infections of horses with equine influenza virus elicited the production of inflammatory cytokines such as INF-α, IL-1β, IL-6, and TNF-α." (PMID 21592354, 2011). "TNF-α, IL-1β and NOS2 are produced by macrophages in response to infection with Mtb, while IFN-γ is produced by dendritic cells and various lymphoid cells, including lymphoid cells of the innate immune response." (PMID 21364878, 2011). "scSIV-LMP1 infection resulted in a significant increase in IL-1β, IL-6, IL-8, IL-10, IL-12p70 and TNF, while scSIV-LMP1-CD40 infection resulted in increase in IL-1β, IL-6, IL-8, IL-10 and TNF at various time points." (PMID 21592361, 2011). "At 10 weeks post-infection BCG vaccinated animals exhibited very low levels of all the cytokines studied (IFNγ, TNFα, TGFβ, IL10 and IL12)." (PMID 21533158, 2011). "After 48 h of infection, these cells were transfected with CYLD along with NF-κB luciferase reporter and treated with TNFα for 4 h after 22 h of transfection." (PMID 21408173, 2011). "In our study, we demonstrated that stimuli that mimic infection (LPS, SEB or PMA) or pro-inflammatory mediators, as TNF-α or IL-2 or IL-15, induce the cell surface expression of HMGB1 and its secretion at 48 h or 14 days after treatment, respectively." (PMID 21915243, 2011). "Taken together, S.negevensis inhibits both TNF/Chx and STS-induced apoptosis in a time and infection dose-dependent manner." (PMID 21799887, 2011). "In contrast, there was a greater activation of genes such as TNF-α, IL1A, IL8, JUN, ERRFI1 and KLF6 after infection with N. lactamica relative to N. meningitidis." (PMID 22028815, 2011). "Similar to the immune responses analyzed in the spleen, IFNγ and TNFα production by LCMV-specific CD4+ T cells was reduced or even absent in the liver of CD8-depleted mice on day 8 and 11 after infection." (PMID 21966366, 2011). "Experimental infection of pigs with swine influenza virus correlated the clinical signs with the levels of INF-α, interleukin (IL)-6, and tumor necrosis factor-alpha (TNF-α)." (PMID 21592354, 2011). "The lung cells, obtained on day 30 after infection with the H27 strain and cultured in vitro for 48 h, produced significantly higher levels of IFN-γ, TNF-α and NO than the cells infected with P104 strain." (PMID 21738761, 2011).
infection (continued). "In vitro infection of AM with H3N2 or H1N1 virus resulted in even lower percentages of infected cells (up to 7%) than with HPAIV H5N1, while virus production and TNF-alpha induction were comparable." (PMID 21731493, 2011). "Infection of T cells with HIV-1 subtype AE yields more CA-p24 producing cells than equivalent infections with subtype B. On the other hand, TNFα induced activation from latency is reduced for AE compared to B, which thus yield similar end production levels." (PMID 21923919, 2011). "Intracellular expression of cytokines TNF-α, IL-2, and IFN-γ was determined in popliteal lymph node CD4+ and CD8+ T cells during acute FIV infection in controland CD25 depleted cats." (PMID 21364928, 2011). "On day 7 post-infection, protein levels of IFN-γ, TNF-α, and CXCL2 in the adult lung increased with higher doses of SeV." (PMID 22185352, 2011). "Pro-inflammatory cytokines including IL-1β and TNF-α were markedly elevated and sustained in plasma of SIV infected macaques thorough 21 days of infection." (PMID 21464951, 2011). "When subjected to similar intravitreal challenge with B. cereus, eyes of TNFα-/- mice had significantly less MPO and proinflammatory cytokines during the course of infection compared to that of eyes of wild type mice." (PMID 22163046, 2011). "Our results showed that P3 infection enhanced the releases of IL-10 and CCL2 of DCs but suppressed the production of IFN-α and TNF-α." (PMID 21269456, 2011). "Disease associated with highly pathogenic influenza viruses and the clinical manifestations that ensue in humans can be mediated by the proinflammatory response (e.g., TNF-α, IL-6, CCL2, CCL3, and CXCL10) initiated by the host in response to infection." (PMID 21829352, 2011). "Twelve weeks post-infection, the expression levels of IFN-γ, IL-4, IL-10, TNF-α and Arg I were similar in both groups." (PMID 21390155, 2011). "Given that systemic inflammation during per oral infection are induced by pro-inflammatory mediators such as IFN-γ and TNF-α, we investigated the concentrations of these cytokines in the plasma of infected wt and Mif−/− mice." (PMID 21977228, 2011). "Infection with M. tuberculosis induces a robust T cell responseinvolving CD4+ and CD8+ T cells and the effectorcytokines IFN-γ and TNF, which are all essential for control of infection, yet adaptiveimmunity fails to eradicate M. tuberculosis." (PMID 21637811, 2011). "Following this, by day 60 post-infection, the level of IFN-γ and IL-12 expression induced by the H27 strain had reduced whereas the expression of iNOS and TNF-α remained stable." (PMID 21738761, 2011). "Comparisons across age groups following infection revealed that expression of MIP-1α, MCP-1, IL-10, TNF-α and IFN-γ were significantly increased by infection in preterm lambs compared to full-term lambs." (PMID 21827668, 2011). "Infection of PCPECs from the physiologically relevant basolateral side with S. suis strain 10 (MOI 10) or apical and basolateral stimulation with TNFα (10 ng/ml) leads to significant PMN transmigration." (PMID 21592385, 2011). "Poly(I-C) induction of genes involved in alerting the innate immune system to the infectious threat, including TNF-alpha, IL-1 alpha and beta, CCL5 and IL-6, were suppressed by infection with live MPV." (PMID 21267444, 2011). "Infection of mice with T. gondii elicits a dominant Th1 response involving interferon-gamma (IFN-γ), interleukin-12 (IL-12), IL-18, and tumor necrosis factor alpha (TNF-α)." (PMID 21957440, 2011). "Two or five days after MAb treatment (day 6 or 9 after infection), serum was harvested and levels of relevant cytokines (IFN-γ, TNF-α, IL-10, IL-12 p40, IL-17, and IL-18) were measured by bioplex assay." (PMID 22144897, 2011). "We also assessed the possibility of estimating threshold levels of TNF-alpha and SOD-1 to discriminate between asymptomatic and symptomatic infection." (PMID 20386593, 2010).
infection (continued). "Mice infected with CO92ΔyopH elicited a robust pro-inflammatory cytokine response at 24 h post-infection, characterized by 349 ± 43 pg/ml of TNF-α and 461 ± 35 pg/ml of IL-1β in the BALF of these mice 24 h post-infection (p = 0.001 in comparison to CO92)." (PMID 20565713, 2010). "As for H5N1/2004 infection, CCL-5/RANTES and CXCL-10/IP-10 were found to be induced to >1000 folds; whereas TNF-α and IL-8 were expressed at 200-300 folds." (PMID 21108843, 2010). "We show that these memory CD4+ T cells persist in an activated state, produce the inflammatory cytokines TNFα and IFN-γ, and are more protective than “resting” memory CD4+ T cells obtained from mice in which the infection has been eliminated." (PMID 21124875, 2010). "Briefly, mice were treated with monoclonal antibodies to TNF-α, IL-1β, TNF-α+IL-1β, or the appropriate control IgG one day prior to infection and then every third day for the course of the infection." (PMID 20565713, 2010). "For instance, neutrophils, TNFα and IFNγ are far more important for controlling primary versus secondary LVS infection." (PMID 20967278, 2010). "In contrast, the pro-inflammatory cytokines, TNF-α, IFN-γ, IL-1β, IL-6 and IL-12p70 only became detectable in the blood at 12 h post-infection and peaked by 72 h." (PMID 21124939, 2010). "THP-p89 cells were established by infection with recombinant HIV-p89-GFP virus (dual tropic) and latent cells were negatively selected by FACS and verified by treatment with either TNF-α (10 ng/ml) or TSA (100–300 nM)." (PMID 20585398, 2010). "Immunohistochemical studies of the brain and immunoblot of brain lysates at 4 weeks post-infection revealed protein expression of NOS2 and TNF-α in both CD40−/− and control mice." (PMID 21217818, 2010). "In summary, up-regulation of mRNA for TNF-α, CCL-5/RANTES, and CXCL-10/IP-10 was found to be more prominent during the early phase of infection with H5N1/2004 and H9N2/1997 viruses than those induced by H1N1/2002 virus." (PMID 21108843, 2010). "In the absence of YopH, the host responds to the presence of Y. pestis with an early pro-inflammatory response, namely, an increase in TNF-α and IL-1β in the BALF at 24 h post-infection, which diminishes in magnitude by 48 h post-infection." (PMID 20565713, 2010). "Nonetheless, stimulation with infection induced MPs promoted significant up-regulation of CD40 expression and production of TNF by macrophages." (PMID 20126448, 2010). "This was first addressed by addition of human TNF-α-specific, neutralizing antibodies (5 μg/ml) to the culture media of THP-1 cells during and after infection." (PMID 20421951, 2010). "A neutralizing TNF-α antibody, infliximab (4 μg/ml, Sigma), was then used to treat MKN45 and HGC27 cells after an infection by 26695, and the induction of CXCR4 was inhibited significantly (P < 0.01, respectively)." (PMID 20699000, 2010). "Compared to WT Mtb, infection of primary macrophages with Tn:Rv0431 resulted in secretion of much larger amounts of IL-10, IL-6, MCP-1, IL-12p40 and TNFα as judged by ELISA and higher levels of transcripts for GM-CSF and COX-2 as measured by qRT-PCR." (PMID 21170273, 2010). "RAG° mice receiving chronically stimulated T cells also had higher levels of TNFα, IFN-γ and IL-10, in plasma at day 7 of infection, than those receiving rested T cells." (PMID 21124875, 2010). "As enhanced immunity in this model is also associated with a decrease in pro-inflammatory cytokines, the levels of TNF-α and IL-6 were assessed in T. muris E/S restimulated MLNC culture supernatants during infection." (PMID 19950176, 2010). "Although no significant cytokine/chemokine induction was observed during the early phase of H1N1 infection; IP-10/CXCL-10, TNF-α, TGF-β2, CCL-5/RANTES, IL-8, and IL-6 were found to be 4-450 folds induced during the late phase of infection." (PMID 21108843, 2010).